IL18 (interleukin 18)
Diseases named in the same sentence as IL18 in open-access papers (continued):
Sharing a sentence is not in itself a finding about the gene and the disease.
colitis (continued). "Thus, we next assessed whether IL-18 directly contributes to colitis recovery induced by infliximab." (PMID 35383266, 2022). "We asked whether GSDMD promotes IL-18 release during colitis." (PMID 34721422, 2021). "Similarly, the roles of ASC, Caspase 11, IL-18, and IL-1β in colitis remain debatable." (PMID 34721422, 2021). "Interestingly, colitis and carcinogenesis susceptibility with NLRP6, ASC or IL-18-deficient mice could be transferred to naive wild-type mice by cross-fostering and cohousing the mice together, leading to a dysbiotic gut microbiota." (PMID 34571825, 2021). "However, genetical knocking out of IL-18 in the whole body or blocking of IL-18 receptor enhances the sensitivity to chemicals which induces colitis in mice, suggesting that acetate contributes to maintaining the epithelial barrier via NLRP3 signaling, followed by IL-18 production." (PMID 34299233, 2021). "Thus, NLRC4 inflammasome-mediated production of IL-1β and IL-18 might be the key factors protecting the host from colonic inflammation and infection." (PMID 33808793, 2021). "Importantly, neutralization of IL-18 with anti-IL-18 antibodies or IL-18BP is effective in both dextran sodium sulfate (DSS) and trinitrobenzoic sulfonic acid (TNSB)-induced models of IBD and reduces intestinal IFNγ and TNFα, demonstrating IL-18 as a pivotal mediator in experimental colitis." (PMID 33823154, 2021). "In addition, a protective role for IL-18 has been previously reported in a colitis model in mice." (PMID 34661529, 2021). "Moreover, butyrate increases interleukin 18 (IL-18) expression in epithelial cells, increases the IL-10 expression in dendritic cells and macrophages, and enables them to induce the differentiation of Tregs, thereby conferring protection against colitis." (PMID 33936926, 2021). "Likewise, Il18‐ and Il18r1‐deficient mice display increased susceptibility to DSS‐induced colitis." (PMID 34705319, 2021). "Furthermore, it has been shown that IL-18 blockade, by using either neutralizing anti-murine IL-18 antiserum or by the administration of an adenovirus expressing IL-18 antisense mRNA, diminishes inflammation in murine models of colitis." (PMID 33435303, 2021). "Furthermore, the activated GSDMD promoted the release of interleukin-18 (IL-18), but not the transcript or maturation level of IL-18, which in turn mediated goblet cell loss to induce colitis development." (PMID 34721422, 2021). "There have been numerous reports suggesting that IL-18 could suppress colitis, which indicates that IL-18 may be involved in the repair of the intestinal epithelial layer by maintaining an appropriate level of epithelial cell proliferation during acute experimental colitis." (PMID 33143375, 2020). "In addition, it has been reported that blockage of IL-1β or IL-18 reduces colitis." (PMID 30823406, 2019). "Importantly, despite studies on animal models suggested that reduced IL-18 levels, as downstream effect of NLR proteins alterations, might be critically responsible of increased susceptibility to colitis and CAC, data on humans showed opposite results." (PMID 29868004, 2018). "Likewise, treatment with fraxinellone, a natural lactone endowed with immunosuppressive activity, significantly reduced weight loss, diarrhea and colonic macroscopic damage, as well as myeloperoxidase, alkaline phosphatase, and colonic TNF, IL-1β, IL-6, and IL-18 levels in DSS-induced colitis mice." (PMID 28179906, 2017). "In conclusion, these results suggest that the NLRP3 inflammasome may have a protective effect on Th2 cytokines- and immune system-mediated experimental colitis; both the inflammasome derived IL-1β and IL-18 contribute to this protection via different mechanisms." (PMID 27966619, 2016). "Therefore, we hypothesized that binding of TXNIP to NLRP3 activates the inflammasome, which causes autocleavage of caspase-1 and the release of mature cytokines IL-1 beta and IL-18 during colitis." (PMID 23915129, 2013).
colitis (continued). "Colonic tissues from DSS‐induced colitis models exhibited significantly increased TNF‐α, IL‐1β, and IL‐18 levels relative to healthy controls (p < 0.01)." (PMID 40994452, 2025). "In colitis, mice infected with Helicobacter pylori activate NLRP3 and IL-18 processing, which is sought to protect against colon inflammation." (PMID 41376623, 2025). "Regarding IL-18, sanguinarine relives colitis by inactivating NLRP3-Caspase1/IL-1β pathway, which in turn upregulates IL-18 to exert proinflammatory effects." (PMID 40092732, 2025). "In our study, SC significantly reduced TNF-α, IL-1β, IL-8, and IL-18 levels in UC mice, reinforcing its anti-inflammatory potential against DSS-induced colitis." (PMID 39936162, 2025). "The Nlrp3 inflammasome mediates intestinal inflammation in UC by sensing stress, promoting the secretion of IL-1β and IL-18, epithelial damage, and immune activation, and is upregulated in DSS-induced colitis." (PMID 40995471, 2025). "Studies in murine DSS-induced colitis models show that CST treatment significantly reduced colonic levels of pro-inflammatory cytokines such as IL-1β, IL-6, IL-18, and TNF." (PMID 40370467, 2025). "Blocking the NAD+ salvage pathway inhibited the secretion of IL‐1β, IL‐6, IL‐8, IL‐18, and TNF‐α in the serum and reduced the expression of TNF‐α in the tissues of F. nucleatum‐infected IFX‐treated DSS‐induced colitis mice." (PMID 39739648, 2025). "Another study tested the efficacy of a monoclonal anti-mature IL-18 antibody in DSS colitis mice found that it improved acute and chronic DSS colitis, reduced production of IFNγ and TNFα and ameliorated the epithelial cell barrier." (PMID 40642091, 2025). "MAP3K2, a member of the MAP3K family, plays a pivotal role in the IL-18/MAP3K2/JNK pathway, which is essential for T-cell immunity in the intestine and shows promise as a new target for intervention in T-cell-mediated colitis." (PMID 38612276, 2024). "The research discovered that klebsiella pneumoniae can stimulate the generation of fully developed IL18 in colon epithelial cells and gut organoids, leading to colitis and enhancing DSS-induced colitis." (PMID 38674791, 2024). "In patients with colitis, butyrate induces the release of IL-18 from colon epithelial cells by activating GPR109A, thereby participating in the regulation of colitis and colon cancer." (PMID 39256239, 2024). "A severe enhancement in acute and recurrent colitis as well as the progression of CAC was observed in rodents lacking NLRP3, Pycard, and Casp-1, which was partially induced by suppressed IL1 and IL18." (PMID 38892354, 2024). "The latest research shows that secoisolariciresinol diglucoside alleviates colitis by inhibiting NLRP1 inflammasomes, correlating with reduced IL-1β, IL-18, and TNF-α levels in DSS-induced colitis mice." (PMID 38455052, 2024). "In the current DSS-induced colitis model, we found that LRRK2 G2019S promotes inflammasome activation, resulting in elevated production of IL-1β and IL-18 in the gut epithelium." (PMID 38607004, 2024). "IL-18 signaling from epithelial cells to Tregs is necessary for defense against colitis in the RAG transfer paradigm, and it has been shown that IL-18 promotes Treg reparative activity through amphiregulin." (PMID 36992283, 2023). "Pretreatment with IL-18 reduced inflammatory infiltration and increased the MUC2 and TFF-3 production in mice with dextran sulfate sodium-induced colitis." (PMID 37383609, 2023). "In mouse colitis model, MCC950 was demonstrated to act on NLRP3 by inhibiting ASC oligomerization and caspase-1 dependent activation of IL-1β and IL-18, and reducing the levels of pro-inflammatory cytokines." (PMID 37681916, 2023). "VAD mice demonstrated severe experimental colitis and increased expression of inflammasome-related proteins (caspase-11, GSDMD, NLRP3, ASC, caspase-1, IL-1β, and IL-18) in the colonic LP." (PMID 37240022, 2023).
colitis (continued). "Using caspase-1/11-/-, NLRP3-/-, NLRC4-/-, IL18-/-, and IL22-/- mice, we showed that KLPJ-mediated colitis occurred through activation of caspase-11, and was dependent on IL18 and partly on IL22." (PMID 36436756, 2023). "Mice treated with SCH experienced significant weight gain, effectively alleviating the severity of colitis, and decreasing the levels of inflammatory factors such as TNF-α, IL-1β, IL-18, IL-6, and other related proteins (NLRP3, Caspase-1, SGK1) in UC mice." (PMID 37674245, 2023). "In vivo data showed that IL-18 inhibition, or IL-18R abrogation from intestinal epithelial cells (IECs), protects mice from Dextran Sulfate Sodium (DSS)-induced colitis." (PMID 37891577, 2023). "In a mouse model of colitis induced by dextran sodium sulfate, the NLRP3 inflammasome was activated and shown to be required for production of IL-1β and IL-18, and for dextran sodium sulfate-induced colitis." (PMID 36669831, 2023). "However, on the other hand, IL-18 is thought to promote the ability of colitis by inducing inflammatory mediators such as TNFα and chemokines, inhibition of IL-18 has also been shown to trigger protection in experimental colitis, supporting the role of IL-18 in exacerbating colitis." (PMID 35677444, 2022). "Thus ERS-induced mucin depletion seems to be a relevant pathogenetic mechanism of colitis in IL-10 deficient mice; our results demonstrating a significantly reduced number of goblet cells and expression of MUC-2, IL-18, WFDC2 and Xbp-1 in IL-10 deficient mice at young ages support this hypothesis." (PMID 36699599, 2022). "Mice treated with MCC950, a specific NLRP3 inhibitor, experienced resolution of acute or chronic colitis by inhibiting ASC oligomerization, caspase-1 dependent activation of IL-1β and IL-18, and reducing pro-inflammatory cytokines." (PMID 36199683, 2022). "The mRNA expressions of NLRP3, ASC, caspase-1, GSDMD, IL-18, and HMGB1 were shown to increase in different extents in colitis tissues than in control tissues, whereas SM934 treatment decreased the expression of these genes." (PMID 36120344, 2022). "Mice with DSS-induced colitis exhibited more anxiety and less social behaviour than control mice and occurred in parallel with increased circulating IL-6, NPY, and IL-18 levels as well as an increase in hypothalamic Cox-2 mRNA." (PMID 34983592, 2022). "After MSC-Exo treatment, the colon length in colitis mice increased; colon inflammatory injury decreased; TNF-α, IL-6, IL-1β, IL-17, and IL-18 levels decreased; and Claudin-1, ZO-1, and IκB levels increased." (PMID 34249964, 2021). "The major components and effector molecules of the inflammasome, such as NLRP3, ASC, AIM2, Caspase 1, Caspase 11, IL-18, and IL-1β, play important roles in DSS-induced colitis." (PMID 34721422, 2021). "The levels of proinflammatory cytokines, including TNF-α, IL-6, interferon-γ (IFN-γ), interleukin-18 (IL-18) and interleukin-17a (IL-17a), were significantly increased in DSS-induced colitis mice (P < 0.05 vs. CON)." (PMID 34675239, 2021). "It was found that serum TNF-α, IL-6, IL-18 and IL-1β levels in DSS induced colitis mice model was significantly higher than those in the control normal group." (PMID 34628369, 2021). "Mice fed on an MACs-deprived diet exhibited severe colitis and increased intestinal permeability induced by DSS along with less serum IL-18 levels in mice." (PMID 34299233, 2021). "SCFA acetate binding to metabolite‐sensing receptors GPR43 and/or GPCR109A has been shown to mediate a protective effect against colitis and drive activation of NLRP3 inflammasome in epithelial cells, showing caspase 1 activation and secretion of IL‐18." (PMID 33682108, 2021). "Treatment with the NLRP3-dependent procaspase 1, IL-1β, and the IL-18 inhibitor Fclla-2 can reduce colon inflammation in mice, and the NLRP3 inflammasome can initiate and promote the inflammatory response in colitis." (PMID 34408782, 2021).
colitis (continued). "Compared with the DSS induced colitis mice model group, administration of Schisandrin B more significantly reduced the serum TNF-α, IL-6, IL-18 and IL-1β levels in DSS induced colitis mice model." (PMID 34628369, 2021). "SPF and SPF + P mice were administered daily with recombinant IL-18 (rIL-18) or vehicle intraperitoneally (i.p.)starting 2 days prior and during the DSS colitis." (PMID 32433514, 2021). "The mRNA expression of IL-1β, IL-18, IL-6, TNF-α, IFN-γ, ICAM-1, and VCAM-1 was markedly (all p < 0.01) up-regulated in DSS-induced colitis group, while the IL-10 expression was significantly (p < 0.01) down-regulated." (PMID 33859564, 2021). "Importantly, decreased IL-18, and to a lesser extent IFNγ, production was evident in Casp11−/− mice at 2 weeks, which may be ultimately responsible for defective IL-22 production observed in these mice during both experimental colitis and CAC." (PMID 30538296, 2019). "Recent studies, in this regard, have shown that intestinal epithelial cell (IEC)-produced IL-18 controls intestinal barrier function and promotes DSS-induced colitis by inhibiting differentiation, and promoting depletion, of goblet cells." (PMID 29601578, 2018). "Our results are in agreement with a recent report that demonstrated that ICE-produced IL-18 contributes towards defective intestinal barrier function and inflammation in DSS-induced colitis in mice." (PMID 29601578, 2018). "In fact, authors suggest that the role of AIM2 in colitis is to control the anti‐microbial peptide production (such as α‐ and β‐defensins) in IEC, and to regulate tissue repair, activating an IL‐18‐dependent pathway." (PMID 30098204, 2018). "However, overexpression of IL-18 may allow colitis to enter a chronic phase." (PMID 28360909, 2017). "To examine the effects of MALT1 inhibitors on the cytokine expression in acute DSS colitis model, we measured the levels of IL-1β, IL-6, TNF, IFN-γ, IL-17A and IL-18 in colons of mice following induction of colitis and treatments with MALT1 inhibitors." (PMID 27105502, 2016). "Of note, the dynamics strikingly differed between IL-1β and IL-18 during the development of OXA-induced colitis, whereas exogenous administration of either cytokine had a protective effect against the colitis." (PMID 27966619, 2016). "Of note, in the colitis model, IFN-γ correlated to IL-18 production and was reduced in the Asc−/− mice when compared to WT mice (234 ± 66 to 1831 ± 426 pg/ml, p = 0.001)." (PMID 25115174, 2014). "In the current work we assessed the severity of colitis via an increase in colonic MPO content, colon weight and circulating IL-6 and IL-18 levels as well as by a decrease in colon length and body weight." (PMID 25414650, 2014). "Of note, IL-18 uses MyD88 as a downstream signal transduction effector and MyD88 signaling has been shown to have a protective role in the development of AOM/DSS colitis." (PMID 23606794, 2013). "Interleukin 18 (IL18; position 50.4Mb) has been shown to modulate response to chemically-induced colitis in mice." (PMID 21311099, 2010). "Similarly, in DSS-induced colitis, MHV-68 infection resulted in significant expression of GSDMD, NLRP3, IL-1β, and IL-18 in peritoneal macrophages." (PMID 40041420, 2025). "Given that IL-18 is found in elevated levels in UC patients, a study that used wild type (WT), IL-18-/-, and IL-18R-/- mice in DSS colitis model found that IFNγ production and IL-17 producing CD4+ T cells were reduced in the colons of both knockout models, along with less severe colitis than WT." (PMID 40642091, 2025). "Clinical activity was assessed using the Simple Clinical Colitis Activity Index (SCCAI), quality of life using the Inflammatory Bowel Disease Questionnaire (IBDQ-32), and inflammatory status using serum interleukin-18 (IL-18), C-reactive protein (CRP), and erythrocyte sedimentation rate (ESR)." (PMID 41235106, 2025).
colitis (continued). "Moreover, our DSS-induced colitis mice increased the levels of proinflammatory cytokines including IL-1β, TNF-α, IFN-γ, IL-17, and IL-18, which have been shown to increase in IBD patients." (PMID 40224484, 2025). "Additionally, experimental murine colitis models demonstrated that neutralizing antibodies against TNF-α, IL-12, or IL-18 prevent the onset of colitis which further indicate that proinflammatory immune responses predominate in inflamed mucosa." (PMID 39234241, 2024). "IL-18 stimulates the production of IFN-γ and Th1 responses that can promote colitis." (PMID 35838945, 2023). "While this demonstrated a potential pathogenic contribution for IL-18 in some individuals expressing an NLRC4V341A variant, the mechanisms underlying NLRC4V341A-associated IL-18 production and subsequent colitis development are not known." (PMID 38090573, 2023). "This is supported by the fact that, the knock-out of IL-18 in endothelial cells, hematopoietic cells or in intestinal epithelial cells was found to abrogate DSS-induced colitis, while the knock-out of IL-18R was only protective when present in intestinal epithelial cells." (PMID 37645250, 2023). "Analysis of cytokines predicted to activate Ifng expressing CD4+ T cells in CPI colitis included IL2 (z score 4.7, P < 1.0 × 10−27), IL7 (z score 3.8, P < 9.8 × 10−19), IL15 (z score 3.4, P < 5.2 × 10−34), IL18 (z-score 2.0, P < 4.0 × 10−25) and IL23A (z-score 2.6, P < 2.1 × 10−31)." (PMID 37872166, 2023). "Exogenous administration of IL-1β reduces the expression of colonic Th2 cytokines IL-4 and IL-13 and improves colitis, while exogenous IL-18 also reduces the severity of colitis but does not affect the expression of Th2 cytokines." (PMID 37370025, 2023). "In this respect, considering the effective treatment of a critically ill neonatal AIFEC patient with recombinant IL-18BP, it is quite remarkable that additional IL-18BP deletion did not allow IL-18 to provoke spontaneous colitis in NLRC4V341A/V341A mice." (PMID 38090573, 2023). "The in vivo evidence for NLRP6 inflammasome formation was provided by the demonstration that Nlrp6−/− mice have reduced serum IL-18 levels under steady-state conditions and after dextran sulfate sodium (DSS)-induced colitis compared with that of wild-type (WT) controls." (PMID 33910012, 2021). "After colitis induction, the KD protected intestinal barrier function, and reduced the production of RORγt+CD3− group 3 innate lymphoid cells (ILC3s) and related inflammatory cytokines (IL-17α, IL-18, IL-22, Ccl4)." (PMID 33888680, 2021). "Consistently, blockade of IL‐18 by administration of a monoclonal antibody or anti‐sense IL‐18 mRNA could alleviate DSS‐ and trinitrobenzene sulfonic acid‐induced colitis in mice due to decreased production of IFN‐γ and TNF." (PMID 33491282, 2021). "Besides differences in cytokine and chemokine production during DSS colitis, we also observed that P. intestinalis colonization of SPF mice resulted in a decrease of IL-18 levels in colonic tissue before induction of intestinal inflammation." (PMID 32433514, 2021). "In the dextran sodium sulfate (DSS)-induced colitis model, deficiency of ASC, caspase 1, or NLRP6 in mouse colonic epithelial cells reduced serum levels of IL-18 but not IL-1." (PMID 33227973, 2020). "Researchers found that IL-18 mRNA and TNF-α mRNA levels were elevated in DSS-induced colitis, and the administration of pralnacasan significantly reduced the expression of IL-18 mRNA but did not affect the expression of TNF-α mRNA." (PMID 31242947, 2019). "Therefore, the targeting of different sites of IL-18 by antibodies induced by vaccine A and D, plus the different roles of IL-18Rα and IL-18Rβ chain in inducing signaling pathways, might lead to the different effects of vaccine A and D in the amelioration of murine colitis." (PMID 31428451, 2019).